AR (androgen receptor)
Diseases named in the same sentence as AR in open-access papers (continued):
Sharing a sentence is not in itself a finding about the gene and the disease.
tumor (continued). "Because AR represents a potential therapeutic target in BC and AR positivity may reflect the metastatic potential of tumor cells in some of BC subtypes, the aim of our study was to evaluate the AR status of DTCs in a cohort of early BC patients and compare it with the AR status of the PT." (PMID 37902839, 2024). "Thus, PR inhibition of the AR gene could further impact on the effectiveness of the AR as a therapeutic target and contribute to the tumour promoting activity of progestins." (PMID 39088439, 2024). "We hypothesise that the similar proteomic landscape between ERα‐P and ERα‐C tumours could be due to activity of other steroid hormone receptors (SHRs), such as Androgen Receptor (AR), PR, or Glucocorticoid Receptor (GR), now compensating for loss of ERα action." (PMID 37854018, 2024). "Interestingly, while SIRT1 inhibition under androgen deprivation induces cellular senescence, enhancing the efficacy of AR blockade and radiation therapy, its silencing in hormone-responsive LNCaP cells mimics AR inhibition, resulting in smaller tumor formation." (PMID 39796040, 2024). "Therefore, targeting AR signaling by androgen deprivation therapy (ADT) is a mainstay for pharmacological treatment of men diagnosed with PC at an advanced stage or experiencing tumor recurrence after surgery." (PMID 38416822, 2024). "However, when TAMs become pro-tumor, they can transfer cholesterol to tumor cells in vitro by increasing androgen production and AR activation, suggesting the need to limit cholesterol transfer, the MVA pathway, or TAMs as adjuvant therapy in the context of PCa." (PMID 38396837, 2024). "Interestingly, the AR has oncogenic and tumor suppressive activity." (PMID 38902772, 2024). "Combined PD-1 blockade and AR inhibition may result in better tumor suppression." (PMID 38254871, 2024). "Thus, the transcriptional repressor activity of AR might provide one tumor suppressive mechanism by inhibiting potential pro-tumorigenic genes." (PMID 39676172, 2024). "In this study, we determined that the expression levels of HIC1, which are associated with tumor migration, invasion, and metastasis, were associated with TNBC subtypes: basal-like (MDA-MB-468 and HCC38), mesenchymal-like (MDA-MB-231), and luminal androgen receptor (MDA-MB-453)." (PMID 39339179, 2024). "However, the question of whether AR-Vs can drive a distinct transcription program favoring CRPC tumor progression, due to their structural differences from AR-FL, remains debated." (PMID 38687617, 2024). "In the near future, determining the biochemical characteristics of PCa cells differing in androgen sensitivity and AR dependency and evaluating the histopathological characteristics of various types of PCa cells in tumor tissues may help predict the effectiveness of ADT." (PMID 39768760, 2024). "Thus, we conclude that prolonged AR-induced senescence does not incur a classical inflammatory SASP with associated tumor-promoting effects." (PMID 37190127, 2023). "The value of sequencing the entire genome, including non-coding regions, for understanding tumor proliferation mechanisms is shown by the identification of an intergenic enhancer region upstream of AR, that is amplified in 81% of the mCRPC patients and correlates to increased AR expression." (PMID 37031196, 2023). "Thus, AR targeted therapies remain appropriate in these tumours." (PMID 36527470, 2023). "Additionally, AR expression is crucial for tumor cell growth in OSCC." (PMID 37370896, 2023). "In the initial stages, the induction of AR-driven senescence in tumor cells may reduce tumor growth itself, followed by the cumulative effect of promoting cells towards apoptosis en route to senescence due to the combination of senescence therapy with radiotherapeutic and chemotherapeutic protocols." (PMID 37190127, 2023).
tumor (continued). "In order to determine changes in glycosylation associated with AR inhibition but not yet in the state of hormonal resistance, we compared the tumor regions derived from patients with hormone sensitive PCa (n = 80 patients) and patients with hormonally-treated PCa (n = 37 patients)." (PMID 36828904, 2023). "The combined assessment of PR, ER, AR, GATA3, and PD-L1—as a manually predefined five-marker prognosis score—showed strong prognostic relevance (p < 0.0001) and was an independent risk factor (p = 0.0034) in a multivariate analysis including pT, pN, and tumor grade." (PMID 38137396, 2023). "Tumor cellular assays, qRT-PCR, western blot, ChIP, luciferase assays and CRISPR-Cas9 editing methods were performed to mechanistically understand the cooperation of GATA2 with SMAD4 in promoting TGFβ1 and AR signaling and mediating inherited PCa risk and progression." (PMID 37550764, 2023). "Therefore, tumor cells expressing AR or in an environment rich with androgens may be less responsive to cisplatin-based treatment." (PMID 37666817, 2023). "Additionally, we compared the efficacies of VNLG-152R and the most potent deuterated analog, D7, to the efficacies of clinically relevant TNBC drugs, such as docetaxel (DTX) and enzalutamide (ENZ), in mice tumor xenografts MDA-MB-453 of Caucasian female origin with high AR expression." (PMID 37766871, 2023). "Among them, the aberrant signaling mediated by sex steroid receptors (SRs), mainly the androgen receptor (AR), the derangement of growth factor signaling, the release of steroids, growth factors and chemokines by PC cells themselves or tumor microenvironment (TME) counterpart have been hypothesized." (PMID 36941697, 2023). "Finally, we show that targeting small molecules to the condensates formed by AR and, specifically, to the region of sequence that drives its phase separation has an antitumorigenic effect, specific to AR-dependent tumor growth, in an in vivo CRPC model driven by an ‘undruggable’ AR variant." (PMID 38049566, 2023). "Furthermore, these data suggest that the AR and RUNX1 might work together to promote tumor progression, and to be useful for clinical therapeutic decision-making in AR+-TNBC." (PMID 36766786, 2023). "Moreover, in CRPC, decreased androgen levels may relieve AR suppression of genes mediating DNA synthesis, thereby contributing to tumor cell proliferation." (PMID 36768370, 2023). "However, combined administration of pazopanib and enzalutamide significantly suppressed ccRCC tumor growth, suggesting targeting AR with its inhibitor enzalutamide could enhance pazopanib efficacy." (PMID 37037853, 2023). "Hence, our investigation also encompassed the evaluation of VNLG-152R and its deuterated analogs in three distinct tumor xenografts representing diverse racial origins, including both Caucasian and African women, while considering their respective AR expression status." (PMID 37766871, 2023). "Given that compensating hormone synthesis in tumor niche occurs after standard hormone therapy and restrains the efficacies of androgen antagonist drugs, the ability of eliminating all active AR proteins regardless of high hormone environment is an efficient strategy to block AR signaling." (PMID 36893587, 2023). "Moreover, unlike AR antagonist agents whose efficacy can be attenuated by high androgen levels, ITRI-90 by degrading the AR proteins, is sufficient to inhibit tumor growth even in high androgen environment, which is present in CRPC tumors resulting from intracrine steroidogenesis." (PMID 36893587, 2023). "In addition, the amplificated AR gene could also be detected in CTCs (circulating tumor cells) of patients with CRPC." (PMID 36674820, 2023). "However, radiation-induced up-regulation of the androgen receptor (AR) and tumor-related neo-angiogenesis may be prime targets for the synergistic effects of C-AHT." (PMID 37444473, 2023).
tumor (continued). "Moreover, the crosstalk between AR signaling and immune cells within the tumor microenvironment extends to the involvement of the MNK1/2-eIF4E axis, which plays a crucial role in regulating mRNA translation of pro-proliferative and anti-apoptotic genes in cancer." (PMID 37646236, 2023). "Also, we found that TMPRSS2 was positively related to AR and negatively associated with PD-1 and PD-L1 in LUAD tumor tissue (AA, AC), suggesting that TMPRSS2 agonists might be an immunomodulator of LUAD to anti-PD-1 based immunotherapy combination therapies." (PMID 36992839, 2023). "Unfortunately, resistance mechanisms ultimately develop due to alterations in the AR pathway, such as gene amplification or mutations, and also the emergence of alternative pathways that render the tumor less or, more rarely, completely independent of androgen activation." (PMID 36768610, 2023). "Additionally, AR was also shown to promote cancer stem cell growth, and treatment with the antiandrogen enzalutamide decreased the formation of mammospheres in vitro and reduced tumor growth in vivo." (PMID 37835396, 2023). "In addition, in mice with various androgen status, the overexpression of AR enhanced tumor growth." (PMID 36142861, 2022). "The alteration of the AR cistrome with the acquisition of resistance to the second generation antiandrogens indicates another resistance mechanism that the reprogramming can provide cancer cells the opportunity to develop AR-independent mechanisms of tumor growth." (PMID 36430730, 2022). "Therefore, AR’s expression and function are often investigated in cell lines and tumor specimens." (PMID 36142861, 2022). "Therefore, the tumor’s reliance on AR signaling may also dictate the role that ERG plays during disease progression." (PMID 36212399, 2022). "Also, canonical AR transcriptional activity decreases along with tumor progression." (PMID 35350771, 2022). "However, the AR– group contained the healthy controls (n = 15) and tumor samples (n = 96); therefore, no further classification of these groups was possible based only on AR mutation." (PMID 35053623, 2022). "Furthermore, in silico target prediction and pathway enrichment analyses based on differentially expressed miRNA unraveled a putative association between AR and two key pathways of breast tumorigenesis: VEGF induced angiogenesis and mTOR associated tumor proliferation." (PMID 36111296, 2022). "Likewise, another keyword, “tumor-infiltrating lymphocyte”, may be an indication of AR’s potential mechanism on BC’s prognosis." (PMID 35800434, 2022). "Therefore, simultaneous targeting of PI3K/mTOR and AR signalling may be of clinical value for LAR tumours." (PMID 36077812, 2022). "Moreover, genomic analyses revealed that only AR protein expression was not sufficient for identifying patients, confirming the necessity of identifying tumor LAR subtypes or AR splice variants in AR antagonist therapy." (PMID 36188535, 2022). "They found that the activation of AR altered the genomic distribution of ER and its important co-activators, leading to the repression of ER-regulated cell cycle genes and upregulation of AR-regulated tumor suppressors, thereby inhibiting proliferation of cancer cells." (PMID 35517428, 2022). "This information could be used in the treatment of BCa through the AR pathway that may act as a mechanism of tumor suppression by downregulating cancer-promoting pathways and preventing cell growth, in a personalized manner, that needs to be further elucidated." (PMID 35568821, 2022). "The AR, by interfering with the function of ERα, may have a tumor suppressor function." (PMID 36499670, 2022).
tumor (continued). "The lack of significant association between tumour grade and AR expression in our study may be a result, at least partly, because of the small sample size among other things." (PMID 36405944, 2022). "Moreover, it has been shown that androgen-mediated AR signals are correlated with the tumor development and progression of cancer, which may obviously justify some sex-specific differences in BC59." (PMID 35022469, 2022). "Therefore, we hypothesized that the combination of ceritinib and enzalutamide would provide enhanced effects on tumor growth inhibiting activity in AR+ TNBCs." (PMID 35768871, 2022). "Furthermore, activated kinases (e.g. Src) can trigger its downstream signal pathways to promote PCa cell survival, proliferation, and metastasis that may eventually bypass the requirement of the AR for tumour progression as we discuss later." (PMID 35832549, 2022). "The AR splicing variant ARV7, which lacks the ligand-binding domain, may be constitutively activated in the absence of androgens and acts as a transcription factor repressing crucial tumor suppressor genes and promoting PC progression." (PMID 36230681, 2022). "Therefore, targeting AR and Brg1 could largely reduce tumor cell growth in OTUD6A-overexpressing PCa cells." (PMID 35233061, 2022). "Furthermore, studies have shown that AR-directed therapy induces tumor response." (PMID 35013318, 2022). "The literature suggests that resistance to ER therapies may be due to tumour adaptation towards androgen dependence and AR signalling instead, and it has been suggested that patients with ER+/AR+ tumours would most likely benefit from combination therapies targeting both receptors." (PMID 36209141, 2022). "Moreover, the tumor cells are positive for ER, PR and androgen receptor (AR), which suggest that hormones may manipulate the occurrence and/or development of AAM." (PMID 36401457, 2022). "Hence, the AR signaling pathway dictates tumor growth and cancer progression." (PMID 35447888, 2022). "Moreover, it has been suggested that AR suppresses tumor growth in ER positive breast malignancies." (PMID 35372016, 2022). "Moreover, the chaperone HSP40/HSP70 axis is responsible for the regulation of the GR receptor, the significantly increased expression of which has been confirmed in enzulamide-resistant CRPC, which is an alternative mechanism of tumor cell resistance to AR-targeted therapies." (PMID 35055079, 2022). "Interestingly, they found that GNE-049 could significantly inhibit the proliferation of AR-positive PCa cell lines and patient-derived tumor xenografts (PDX) models of PCa." (PMID 36060957, 2022). "Tumor resistance to androgen receptor (AR) targeted chemotherapy in metastatic castration resistant prostate cancer (MCPRC) due to intratumoral androgen mutation, expansion, steroid increase, AR splice variant expression, and androgen independent tumor cell development." (PMID 36439106, 2022). "Importantly, AR decoction could inhibit tumor growth and inhibit Wnt/β-catenin signaling in mouse models of CRC xenograft tumors." (PMID 34991661, 2022). "Interestingly, targeting both the PI3K and AR pathways significantly inhibited tumour growth in preclinical models of PTEN resistance and enzalutamide resistance, suggesting potential crosstalk between the pathways and demonstrating the potential for combination therapeutic strategies." (PMID 35668070, 2022). "First, AR signaling may have both oncogenic and tumor suppressive roles." (PMID 35814433, 2022). "However, there are also AR-independent mechanisms, with very low or absent AR expression found in tumor cells that render ADT ineffective and are associated with neuroendocrine (NE) differentiation." (PMID 35582526, 2022). "However, the potential roles of AR in the progression of this tumour remain to be determined." (PMID 35452181, 2022).
tumor (continued). "Interestingly, orthotopic co-inoculation of AR-deficient human prostate stromal cells (WPMY1) and AR-negative CRPC cells (PC-3) in immunocompromised nude mice marginally reduced tumor burden relative to PC-3 tumors grown with human stromal cells expressing functional AR." (PMID 36671452, 2022). "However, since AR status may differ between primary tumor and matched metastases AR testing should be carried out in both specimens to help patient selection for anti-AR therapy." (PMID 36111296, 2022). "The complex interplay between stress, obesity, and circadian disruption may have detrimental effects on the tumor microenvironment and could enhance the stress-related PCa growth pathway, otherwise known as the glucocorticoid-mediated androgen receptor signaling pathway." (PMID 36291899, 2022). "AR expression or dihydrotestosterone (DHT) treatment can decrease the forkhead box O1 (FOXO1) expression and cause FOXO1 phosphorylation through the protein kinase B signaling pathway, which works as a tumor suppressor to BLCA cells metastasis, migration, invasion, and proliferation." (PMID 36468030, 2022). "Therefore, biomarkers of response are also needed to understand how AR agonists and antagonists might be used in different patient populations in diverse biological contexts to increase tumour control." (PMID 35618789, 2022). "In contrast to strongly AR+ TNBC, low-level AR expression has been associated with more aggressive forms of TNBC, suggesting that in at least some subtypes of BC, ADT may have a tumour-promoting effect." (PMID 36376977, 2022). "Similarly, in TCGA whole primary tumor samples proteomics data (n = 105), mir-29c positively correlated with AR and negatively correlated with CD276/B7H3, indicating that AR may upregulate mir-29c and subsequently downregulate its target CD276/B7H3." (PMID 36550153, 2022). "LIN28A can activate AR via c-mycregulation and promotes malignancy of ER-/Her2 + BC, thus providing strong evidence that curcumin can directly or indirectly interact with androgen signaling pathways and can affect tumor progression by regulating androgen signaling." (PMID 33499881, 2021). "In addition, the impact on tumor growth and weight, AR expression, and apoptosis were analyzed." (PMID 34008909, 2021). "Indeed, this inhibitory effect exerted by OB on AR activity could induce tumor cells to promote alternative molecular pathways of proliferation." (PMID 34966687, 2021). "In addition, many studies have found that AR has a wide range of pharmacological activities, including anti-tumor, anti-convulsant, anti-inflammatory, anti-bacterial, anti-arrhythmic, sedative and analgesic, anti-coagulant, and killing properties against the Oncomelania snail." (PMID 34887934, 2021). "Therefore, we used a syngeneic orthotopic mouse model to test the hypothesis that AR suppression using the AR antagonist, enzalutamide, is effective to suppress tumor growth in the brain." (PMID 34094902, 2021). "Thus, there is support for use of ADT in UBC, especially when the tumor expresses AR." (PMID 34768683, 2021). "It is not known whether subclones with such AR mutations pre-exist in a heterogeneous tumor mass (intrinsic resistance) or are indeed induced by the drug treatment." (PMID 33477370, 2021). "Interestingly, when comparing castration-resistant adenocarcinomas to their hormone-sensitive counterparts, even in the AR-positive tumours there was little change in AR copy number (a non-significant increase in 2 cases) and no additional AR mutations." (PMID 34535657, 2021). "AR does not act alone but functions in a complex with other nuclear cofactors and chromatin-associated proteins to drive transcription of genes essential for tumor growth and drug resistance." (PMID 33384381, 2021).